NUP155 (nucleoporin 155)
Description:
Essential component of nuclear pore complex. Could be essessential for embryogenesis. Nucleoporins may be involved both in binding and translocating proteins during nucleocytoplasmic transport.
Synonyms: KIAA0791; N155; ATFB15
Tractability: Antibody: UniProt places it where antibodies can reach, with medium confidence. PROTAC: UniProt records ubiquitination sites on it; ubiquitination databases record sites on it; its protein half-life has been measured.
Gene: Protein-coding gene on chromosome 5 (37,288,137 to 37,371,140, reverse strand). Ensembl gene ENSG00000113569.
Subcellular location: Nucleus, nuclear pore complex; Nucleus membrane
Subcellular location (Human Protein Atlas): Nuclear membrane
Pathways (Reactome):
Disease: Defective TPR may confer susceptibility towards thyroid papillary carcinoma (TPC); HCMV Early Events; HCMV Late Events; NEP/NS2 Interacts with the Cellular Export Machinery; NS1 Mediated Effects on Host Pathways; Nuclear import of Rev protein; Rev-mediated nuclear export of HIV RNA; SARS-CoV-2 activates/modulates innate and adaptive immune responses; Transport of Ribonucleoproteins into the Host Nucleus; Viral Messenger RNA Synthesis; Vpr-mediated nuclear import of PICs
Metabolism of RNA: Transport of Mature mRNA Derived from an Intronless Transcript; Transport of Mature mRNA derived from an Intron-Containing Transcript; Transport of the SLBP Dependant Mature mRNA; Transport of the SLBP independent Mature mRNA; snRNP Assembly; tRNA processing in the nucleus
Metabolism of proteins: SUMOylation of DNA damage response and repair proteins; SUMOylation of DNA replication proteins; SUMOylation of RNA binding proteins; SUMOylation of SUMOylation proteins; SUMOylation of chromatin organization proteins; SUMOylation of ubiquitinylation proteins
Metabolism: IP3 and IP4 transport between cytosol and nucleus; IP6 and IP7 transport between cytosol and nucleus; IPs transport between nucleus and cytosol; Regulation of Glucokinase by Glucokinase Regulatory Protein
Cell Cycle: Nuclear Pore Complex (NPC) Disassembly; Postmitotic nuclear pore complex (NPC) reformation
Cellular responses to stimuli: Regulation of HSF1-mediated heat shock response
Immune System: ISG15 antiviral mechanism
Gene Ontology:
Molecular function: protein binding; structural constituent of nuclear pore
Biological process: nuclear envelope organization; nucleocytoplasmic transport; protein import into nucleus; protein localization to nuclear inner membrane; RNA export from nucleus; transcription-dependent tethering of RNA polymerase II gene DNA at nuclear periphery
Cellular component: membrane; nuclear envelope; nuclear membrane; cytosol; nuclear pore; nuclear pore inner ring
Genetic constraint (gnomAD): Loss-of-function variants: 36 observed, 100.55 expected, observed/expected ratio (o/e) 0.36, 90% interval 0.27 to 0.47. The upper end of that interval is the gene's LOEUF score, 0.47, which puts it in group 2 of 6, group 1 being the genes least tolerant of losing a copy. Missense variants: 1,040 observed, 1,177.5 expected, observed/expected ratio (o/e) 0.88, 90% interval 0.84 to 0.93. Synonymous variants: 401 observed, 415.64 expected, observed/expected ratio (o/e) 0.96, 90% interval 0.89 to 1.05.
Homologues: Orthologues: chimpanzee NUP155 (99% identical), macaque NUP155 (99% identical), pig NUP155 (96% identical), rat Nup155 (95% identical), mouse Nup155 (95% identical), guinea pig NUP155 (94% identical), rabbit NUP155 (94% identical), dog NUP155 (92% identical), tropical clawed frog nup155 (79% identical), zebrafish nup155 (72% identical), Drosophila melanogaster Nup154 (32% identical), Caenorhabditis elegans npp-8 (24% identical).
Diseases named in the same sentence as NUP155 in open-access papers:
NUP155 is named in the same sentence as 39 diseases in open-access papers, as found by Europe PMC text mining. Sharing a sentence is not in itself a finding about the gene and the disease. The quoted sentences say what the papers report.
atrial fibrillation (8 papers, 2011 to 2024). A disorder characterized by an electrocardiographic finding of a supraventricular arrhythmia characterized by the replacement of consistent P waves by rapid oscillations or fibrillatory waves that vary in size, shape and timing and are accompanied by an irregular ventricular response. "To examine the potential association of single nucleotide variants of nucleoporin genes with cardiac disease, we employed a prognostic scoring approach to investigate variants of NUP155, a nucleoporin gene clinically linked with atrial fibrillation." (PMID 32118046, 2020). "The crescent shaped domain within the amino terminal region of NUP155 harbors the clinical R391H and L503F mutations associated with atrial fibrillation." (PMID 32118046, 2020). "One example that depicts Nups requirements is atrial fibrillation (AF) caused by a mutation in the human NUP155 which, in turn, can lead to sudden cardiac death." (PMID 22567364, 2011). "Taken together these results show that NUP155-deficient EBs are prone to electrical instability which may serve as a substrate for atrial fibrillation." (PMID 29848314, 2018). "In addition, it has been found that a mutation in Nup155 leads to atrial fibrillation and sudden death." (PMID 23152829, 2012). "Mutations in human NUP155 have been linked to specific phenotypes including atrial fibrillation (AF), a common cardiac arrhythmia." (PMID 39080077, 2024). "However, mutations to nucleoporin Nup155 are associated with atrial fibrillation." (PMID 36736767, 2023). "For example, the previously reported atrial fibrillation-associated rare NUP155 variants R391H and L503F had respective allele frequencies of 3.977 × 10−6 and 1.193 × 10−5 in gnomAD, setting a precedence for the presence of rare cardiopathogenic NUP155 variants in this cohort." (PMID 32118046, 2020). "For example, previous work using a murine embryonic stem cell (ESC) line containing a heterozygous truncation of the NUP155 gene (nup155+/−) associated with atrial fibrillation (AF) revealed that NUP155 disruption impaired nuclear transport of HSP707." (PMID 31481660, 2019). "Mutation of a central scaffold nucleoporin, Nup155, is responsible for a cardiac disorder referred to as atrial fibrillation (AF)." (PMID 25184662, 2014). "Thus, while the role for miRNA regulation in cardiac development is well understood, the functional relationship of nups and miRNAs may be a contributing and underlying mechanism to explain the idiopathic atrial fibrillation phenotype associated with nup155 deficiency." (PMID 31481660, 2019). "NUP155 is a nuclear pore complex protein that has been identified as a clinical driver of atrial fibrillation, yet the precise mechanism is unknown." (PMID 29848314, 2018). "NUP155, being a critical scaffolding component of the NPC, in a homozygous mutant form has been shown to impair atrial electrical signaling and give rise to clinical atrial fibrillation." (PMID 29848314, 2018).
liver cancer (6 papers, 2019 to 2024). An epithelial or non-epithelial malignant neoplasm that arises from the liver. "Moreover, the targeting of p21 in liver cancer was also demonstrated to be associated with the poor survival of patients through a feedback loop with NUP155." (PMID 39000572, 2024).
hepatocellular carcinoma (5 papers, 2019 to 2024). A malignant tumor that arises from hepatocytes. "NUP155 was reported to involve breast invasive carcinoma and hepatocellular carcinoma." (PMID 39720592, 2024). "High expression of NUP155 was identified in a hepatocellular carcinoma subgroup." (PMID 39720592, 2024).
cardiac hypertrophy (3 papers, 2018 to 2020). "In a model of cardiac hypertrophy, NUP155 was immunoprecipitated with repressive histone deacetylases (HDACs), in line with the gene silencing environment at the nuclear periphery." (PMID 31481660, 2019). "It is of note that NUP155 regulates cardiac hypertrophy through HDAC4, providing additional evidence for the potential role of nups as epigenomic regulators." (PMID 29848314, 2018). "NUP155 may also act indirectly through interactions with histone modifiers for studies in rat models of cardiac hypertrophy, or inferred by electronic protein interaction datasets." (PMID 29848314, 2018).
HIV-1 infection (3 papers, 2018 to 2024). The type species of lentivirus and the etiologic agent of acquired immunodeficiency syndrome (AIDS). "In the combined knockdown cells, the loss of CypA interaction only partially restores HIV-1 infection levels, up to the level of what is observed in the Nup155-single knockdown cells." (PMID 37355754, 2023). "Perturbation of the NUP155 and the Nup93 complex also impacted the effect of CA mutations and CypA on HIV-1 infection." (PMID 30084827, 2018). "The infectivity of WT HIV-1 in the CypA plus Nup155 double knockdown cells is comparable to N74D and P90A HIV-1 infection of the Nup155-depleted cells." (PMID 37355754, 2023). "WT HIV-1 infection is diminished in cells depleted of Nup153 but retains greater infectivity in Nup155-knockdown cells." (PMID 37355754, 2023). "In order to better understand the interrelation between Nup35- and Nup155-dependent infection, we depleted both factors and assessed the effect of CsA treatment on HIV-1 infection." (PMID 37355754, 2023). "As the CypA knockdown data indicated, CsA treatment restores HIV-1 infection in Nup35 knockdown but not Nup155 knockdown cells." (PMID 37355754, 2023). "Overall, manipulations of NUP155 and other Nup93 subcomplex components recapitulated, abolished, or otherwise modified several of the key cell-type- and CA-dependent differences in the effects of CypA and MX2 on HIV-1 infection." (PMID 30084827, 2018). "HIV-2 and SIVmac infection were inhibited by many Nup depletions and both were modestly sensitive to depletions of a number of Nups that did not affect HIV-1 infection (e.g. NUP155, TPR, NUP62, NUP54, NUPL1." (PMID 30084827, 2018). "NUP155 did not bind CA tubes in vitro, suggesting that its effects on HIV-1 infection are indirect." (PMID 30084827, 2018).
breast carcinoma (2 papers, 2012 to 2024). "The specific pathogenic mechanism of NUP155 in breast cancer will be validated in the future." (PMID 38504158, 2024). "The expression of NUP155 mRNA in breast cancer cell lines was significantly higher than that in healthy breast cells." (PMID 38504158, 2024). "Therefore, the differential expression of NUP155 between healthy breast cells (MCF-10 A cells) and three breast cancer cell lines (BT-549, MDA-MB-231, and T-47D cells) was examined using qRT-PCR analysis." (PMID 38504158, 2024).
breast invasive carcinoma (2 papers, 2024). "This study, for the first time, demonstrated that NUP155 was upregulated in breast invasive carcinoma (BRCA) cells and revealed its oncogenic role in BRCA using molecular biology experiments." (PMID 38504158, 2024). "Furthermore, the oncogenic role of NUP155 in breast invasive carcinoma (BRCA) was validated using molecular biology experiments." (PMID 38504158, 2024). "In breast invasive carcinoma (BRCA) cells, NUP155 was detected to be upregulated, and it played a tumorigenic role in BRCA." (PMID 39720592, 2024).
endometrial carcinoma (2 papers, 2021 to 2024). A malignant tumor arising from the epithelium that lines the cavity of the uterine body. "In this study, NUP155 was frequently mutated in various tumors, especially melanoma, endometrial carcinoma, cervical adenocarcinoma, BLCA, and cervical squamous cell carcinoma." (PMID 38504158, 2024).
esophageal squamous cell carcinoma (2 papers, 2020 to 2021). Esophageal squamous cell carcinoma (ESCC) is a type of esophageal carcinoma (EC) that can affect any part of the esophagus, but is usually located in the upper or middle third. "NUP155-positivity correlated with shorter OS in CCC, while esophageal squamous cell carcinoma showed an association between low expression of NUP155 with shorter OS." (PMID 32133296, 2020). "In a gene enrichment and meta-analytic study, NDC1 was reported as one of the critical genes in addition to NUP107 and NUP155 genes regulating esophageal squamous cell carcinoma (ESCC)." (PMID 34970494, 2021).
acute myeloid leukemia (1 paper, 2024). Acute myeloid leukemia (AML) is a group of neoplasms arising from precursor cells committed to the myeloid cell-line differentiation. "In contrast, the NUP155 expression levels in acute myeloid leukemia (LAML), testicular germ cell tumor (TGCT), and thyroid carcinoma (THCA) tissues were downregulated when compared with those in non-cancerous tissues." (PMID 38504158, 2024).
cervical cancer (1 paper, 2017). A primary or metastatic malignant neoplasm involving the cervix. "NUP155 has not been described to be associated with cervical cancer." (PMID 29312619, 2017).
colorectal cancer (1 paper, 2006). A primary or metastatic malignant neoplasm that affects the colon or rectum. "Among the up-regulated genes in colorectal cancer, we found 14 genes involved in signal transduction (TDGF1 and ENC1), transcription (SOX9, MYC, and HGFR/MET), nuclear transport (NUP62, NUPL1, NUP155, KPNA2, RANBP5, CSE1L/CAS, NTF2, and RANBP1) and cellular transport (SLCO4A1)." (PMID 16919171, 2006).
melanoma (1 paper, 2024). A malignant, usually aggressive tumor composed of atypical, neoplastic melanocytes. "The KM survival curve of the GSE78220 cohort revealed that NUP155 upregulation was associated with poor OS in patients with malignant melanoma." (PMID 38504158, 2024). "Therefore, patients with drug-resistant melanoma exhibiting NUP155 upregulation may be suitable for treatment with trametinib." (PMID 38504158, 2024).
mesothelioma (1 paper, 2024). A usually malignant and aggressive neoplasm of the mesothelium which is often associated with exposure to asbestos. "However, NUP155 expression was not significantly different between cancer and non-cancerous tissues in mesothelioma (MESO), pheochromocytoma and paraganglioma (PCPG), and sarcoma (SARC)." (PMID 38504158, 2024).
non-small cell lung carcinoma (1 paper, 2024). A group of at least three distinct histological types of lung cancer, including non-small cell squamous cell carcinoma, adenocarcinoma, and large cell carcinoma. "The frequency of NUP155 alterations was the highest in non-small cell lung cancer (approximately 10%)." (PMID 38504158, 2024).
small cell lung carcinoma (1 paper, 2024). Small cell lung cancer (SCLC) is a highly aggressive malignant neoplasm, accounting for 10-15% of lung cancer cases, characterized byrapid growth, and early metastasis. "The NUP155 expression levels varied in different cancer cell lines with the small cell lung cancer cell line exhibiting upregulated expression levels." (PMID 38504158, 2024).
urothelial carcinoma (1 paper, 2024). A malignant neoplasm derived from the transitional epithelium of the urinary tract (urinary bladder, ureter, urethra, or renal pelvis). "Meanwhile, the KM survival curve of the Imvigor210 cohort revealed that NUP155 upregulation was associated with beneficial OS in patients with urothelial carcinoma." (PMID 38504158, 2024).